FAM161B (FAM161 centrosomal protein B)
Synonyms: C14orf44; FLJ31697; c14_5547
Tractability: Antibody: the Human Protein Atlas places it where antibodies can reach. PROTAC: ubiquitination databases record sites on it.
Gene: Protein-coding gene on chromosome 14 (73,931,501 to 73,950,414, reverse strand). Ensembl gene ENSG00000156050.
Subcellular location (Human Protein Atlas): Nucleoplasm; Plasma membrane; Cytosol; Vesicles
Gene Ontology:
Molecular function: protein binding
Biological process: cilium organization
Cellular component: cytoplasmic microtubule; microtubule cytoskeleton; cytoskeleton
Genetic constraint (gnomAD): Loss-of-function variants: 46 observed, 64.19 expected, observed/expected ratio (o/e) 0.72, 90% interval 0.56 to 0.92. The upper end of that interval is the gene's LOEUF score, 0.92, which puts it in group 3 of 6, group 1 being the genes least tolerant of losing a copy. Missense variants: 774 observed, 822.88 expected, observed/expected ratio (o/e) 0.94, 90% interval 0.89 to 1. Synonymous variants: 284 observed, 313.6 expected, observed/expected ratio (o/e) 0.91, 90% interval 0.82 to 1.
Homologues: Orthologues: chimpanzee FAM161B (99% identical), dog FAM161B (78% identical), pig FAM161B (78% identical), rabbit FAM161B (72% identical), mouse Fam161b (71% identical), rat Fam161b (69% identical), guinea pig FAM161B (68% identical), macaque FAM161B (66% identical), tropical clawed frog fam161b (33% identical), zebrafish fam161b (30% identical). Paralogues in human: FAM161A (26% identical), TSGA10IP (14% identical).
Diseases named in the same sentence as FAM161B in open-access papers:
FAM161B is named in the same sentence as 4 diseases in open-access papers, as found by Europe PMC text mining. Sharing a sentence is not in itself a finding about the gene and the disease. The quoted sentences say what the papers report.
adenoma (1 paper, 2012). A neoplasm arising from the epithelium. "Results showed good agreement with the microarray analysis, GCG, NMES-1, and FAM161B genes were downregulated in both the adenoma and the tumor samples, while LRMP showed reduced expression only in the tumor samples." (PMID 23049694, 2012).
colon cancer (1 paper, 2022). "Previous studies have reported that FAM161B was regulated by methylation in colon cancer." (PMID 36290392, 2022).
retinitis pigmentosa (1 paper, 2016). Retinitis pigmentosa (RP) is an inherited retinal dystrophy leading to progressive loss of the photoreceptors and retinal pigment epithelium and resulting in blindness usually after several decades. "This localisation is similar to that of the mammalian protein implicated in retinitis pigmentosa, and is consistent with the suggested role of FAM161b in cargo delivery to photoreceptor outer segments (cilia)." (PMID 27930654, 2016).
FAM161B also shares sentences with these, for which no sentence is quoted: tumor (1 paper).